DDIT3 (DNA damage inducible transcript 3)
Diseases named in the same sentence as DDIT3 in open-access papers (continued):
Sharing a sentence is not in itself a finding about the gene and the disease.
melanoma (47 papers, 1994 to 2025). A malignant, usually aggressive tumor composed of atypical, neoplastic melanocytes. "NVP-AUY922 induced expression of HSP70, GRP78 and DDIT3 (DNA damage-inducible transcript 3) encoding CHOP, thereby increasing endoplasmic reticulum stress and activating unfolded protein response in melanoma cells." (PMID 31659567, 2020). "As with thapsigargin, WX8 induced PERK‐dependent phosphorylation of EIF2A protein and upregulation of ATF4 and DDIT3 proteins in melanoma A375 cells accompanied by translocation of transcription factors ATF4 and CEBPb to the nucleus." (PMID 38414326, 2024). "Consistent with our in vitro findings, genes associated with the ATF4 (e.g., ATF4, DDIT3, PPP1R15A and CHAC1), ATF6 (e.g., ATF6B, CALR, SEL1L, and EDEM1) and XBP1 (e.g., SSR3 and DELR1) pathways were significantly enriched in melanoma TILs compared with healthy blood T cells." (PMID 40335738, 2025). "On the other hand, DDIT3, a mediator of endoplasmic reticulum stress-mediated apoptosis, has not been implicated in melanoma biology to date." (PMID 30769764, 2019). "Interestingly, only WIPI1 and DDIT3 were shared between both CTC fractions and single melanoma cells." (PMID 30769764, 2019). "We analyzed a few of the top DEGs (NRP2, CAPN3, DMBT1, BRAF, DDIT3, PPP1R3C, NF1) using The UCSC Xena platform that has large number of RNA-seq data of normal tissue from healthy individuals (GTEx) and primary tumor and metastatic tissue data from melanoma patients (TCGA)." (PMID 32983966, 2020). "However, DDIT3 was up-regulated as a result of the apoptotic activity triggered by the compound HA15 in melanoma cell lines, as was SEC31A, a gene found up-regulated in MCSP CTC fractions, Altogether, the role of WIPI1 and DDIT3 may indicate common molecular mechanisms in CTC biology." (PMID 30769764, 2019). "It displays strong anti-tumorigenic activity in xenograft mouse models with melanoma cells, which depends on activation of ATF4 and DDIT3, without toxicity in normal cells." (PMID 29290987, 2017).
colorectal cancer (46 papers, 2010 to 2025). A primary or metastatic malignant neoplasm that affects the colon or rectum. "In colorectal cancer cells, the ATF6 transcriptionally active N-terminus increased GRP78, DDIT3 (which encodes CHOP), and EIF2AK3 (which encodes PERK) gene expression and significantly increased apoptotic cells." (PMID 38283278, 2023). "We previously showed that ferrichrome induced colorectal cancer apoptosis through the activation of the DDIT3 signaling." (PMID 33407519, 2021). "We identified Lactobacillus casei-derived ferrichrome as a mediator of the bacterial anti-tumor effect of colorectal cancer cells through the upregulation of DDIT3." (PMID 33407519, 2021). "Ferrichrome activated the DNA damage inducible transcript 3 (DDIT3) signal and induced apoptosis in colorectal cancer cells." (PMID 33407519, 2021). "ICG-001 activates an early ER stress pathway including activating transcription factor 4 (ATF4), DNA damage inducible transcript 3 (DDIT3), and tribbles pseudokinase 3 (TRIB3) in sensitive as opposed to resistant colorectal cancer cell lines." (PMID 29290987, 2017).
gastric cancer (46 papers, 2014 to 2025). A primary or metastatic malignant neoplasm involving the stomach. "In our previous studies, we established that ferrichrome induces the expression of DDIT3, an apoptosis-associated transcription factor, thereby demonstrating its anti-tumor properties that promote apoptosis in colon and gastric cancer cells." (PMID 38545201, 2024). "Moreover, NCAPD3 loss activates IRF7 and DDIT3 to regulate apoptosis in gastric cancer cells." (PMID 38711992, 2024). "Overexpression of DDIT3 promotes stemness of cancer stem cells in gastric cancer by regulating CEBPβ." (PMID 38474084, 2024). "Our previous research had demonstrated the induction of DDIT3 by ferrichrome treatment in colorectal and gastric cancer cells." (PMID 38545201, 2024). "In clinical studies involving human specimens, low DDIT3 expression has been identified as a poor prognostic factor in gastrointestinal cancers, including gastric cancer." (PMID 38545201, 2024). "The study found that through the microarray screening, DDIT3 showed abnormally expressed in gastric cancer tissue compared to normal tissues." (PMID 37371530, 2023). "CPNE1 influenced cell proliferation, cytochrome c-mediated caspase cascade apoptosis and arrested cell cycle in gastric cancer via DDIT3-FOS-MKNK2 axis." (PMID 37077419, 2023). "Although several studies have demonstrated that HOXA-AS2 promotes tumor proliferation by serving as an “miRNA sponge”, it has also been shown to enhance gastric cancer proliferation by epigenetically silencing the expression of p21, plk3, and DDIT3." (PMID 34511122, 2021). "Long non-coding RNA HOXA-AS2 promotes gastric cancer proliferation by epigenetically silencing P21/PLK3/DDIT3 expression by binding with EZH2 (enhaner of zeste homolog 2)." (PMID 29221147, 2017). "lncRNA HOXA-AS2 promotes gastric cancer proliferation by epigenetically silencing P21/PLK3/DDIT3 expression." (PMID 28881797, 2017). "Methylation inactivation of tumor suppressor genes, such as FLCN and DDIT3, is important for the development of many cancer, such as renal cancer and gastric cancer, but inactivation of these genes may be responsible for the advancement of BRCA." (PMID 31311202, 2019). "Furthermore, DDIT3 expression is significantly upregulated in gastric cancer." (PMID 38911383, 2024). "In addition, DDIT3 promotes cancer stem cell stemness by upregulating CEBPβ in gastric cancer." (PMID 37371530, 2023). "In a study on gastric cancer, it was shown that DDIT3 can directly upregulate the transcription factor CEBPB, thereby increasing the stemness of gastric cancer cells and the expression of stem cell markers: SOX2, NANOG, OCT4, and CD133." (PMID 38710698, 2024). "Therefore, NCAPD3 knockdown may activate IRF7, DDIT3, and HBEGF expression to promote gastric cancer cell apoptosis." (PMID 38711992, 2024).
glioma (40 papers, 2010 to 2025). A benign or malignant brain and spinal cord tumor that arises from glial cells (astrocytes, oligodendrocytes, ependymal cells). "Further, cannabinoid-mediated apoptosis is associated with the upregulation of ATF4, DDIT3, and TRIB3 in cannabinoid-sensitive glioma cells." (PMID 29290987, 2017). "This interplay between CEBPB and DDIT3 may be relevant for glioma therapy development, as DDIT3 induction in response to a range of compounds sensitizes glioma cells to apoptosis (see, for example,)." (PMID 23046790, 2012). "Additionally, DDIT3 was identified in a TCGA worst-prognosis signature (TWPS) comprising 884 genes differentially expressed in worst versus best prognosis gliomas and low DDIT3 levels may be prognostically relevant for MPM." (PMID 25868979, 2015). "As another cannabinoid-triggered upstream ion channel a recent investigation found TRPV4 and a signalling pathway including ATF4, DNA Damage Inducible Transcript 3 (DDIT3), TRB3, Akt and mTOR as mediators of CBD-induced mitophagy in glioma cells." (PMID 35277658, 2022). "In glioblastoma, upregulation of TGase 2 expression by microglia-derived cytokines induces CCAAT-enhancer-binding protein β (C/EBPβ) expression by depleting DNA damage-inducible transcript 3 (GADD153), triggering mesenchymal transdifferentiation of glioma stem cells." (PMID 30297644, 2018). "Whilst phosphorylated eIF2α, ATF4 and DDIT3 were detected in tryptophan-deprived GL261 cells, phosphorylated GCN2 was not consistently observed in three independent studies with GL261 glioma cells cultured in low tryptophan concentrations." (PMID 30466445, 2018). "Specifically, DDIT3, HOXD10, PDE1C and PLS3 were upregulated in GNS cells and expressed at higher levels in glioblastomas with poor prognosis, while PTEN and TUSC3 were downregulated in GNS cells and expressed at lower levels in gliomas with poor prognosis." (PMID 23046790, 2012). "As target genes of three branches, DDIT3 (CHOP) and DNAJB9 (IRE1α-XBP1), but not SEL1L (ATF6) were obviously upregulated in glioma cells after treatment of S4, which declared ATF6 was not the main activated branch." (PMID 37386564, 2023).
atherosclerosis (38 papers, 2012 to 2025). A disease characterized by the build-up of fatty material and calcium deposition in the arterial wall resulting in partial or complete occlusion of the arterial lumen. "On the other hand, while searching for a set of genes associated with the MAPK signaling pathway, we found a group of four DEG members of this pathway: PLA2G4A, IL1A, RASGRP3, and DDIT3, which are molecules related to inflammation, apoptosis, signal transduction, and atherosclerosis." (PMID 40332370, 2025).
pulmonary fibrosis (35 papers, 2013 to 2025). Chronic progressive interstitial lung disorder characterized by the replacement of the lung tissue by connective tissue, leading to progressive dyspnea, respiratory failure, or right heart failure. "Together, these data demonstrate that inhaled miR‐30a attenuated bleomycin‐induced pulmonary fibrosis by promoting myofibroblast de‐differentiation through the downregulation of the CNPY2/PERK/DDIT3 signaling pathway." (PMID 40119620, 2025).
glioblastoma (34 papers, 2012 to 2026). The most malignant astrocytic tumor (WHO grade IV). "Overexpression of DNA damage-inducible transcript 3 (DDIT3/CHOP) in human glioblastoma, pancreatic, and Burkitt’s lymphoma cells links ATF4 to ferroptosis-associated diseases, such as Burkitt’s lymphoma and diabetic myocardial IRI." (PMID 39737174, 2024). "The significantly increased DDIT3 expression played a crucial role in the investigation of the mechanism responsible for the K8-induced glioblastoma cell apoptosis." (PMID 27852055, 2017). "In highly malignant glioblastomas, the E3 ubiquitin ligase RNF138 has been shown to mediate ribosomal protein S3 (rpS3) ubiquitination, thereby inhibiting rpS3/DDIT3-mediated apoptotic signaling when stimulated by radiation and inducing radioresistance in glioblastoma (GBM) cells." (PMID 38137461, 2023). "Furthermore, a study in glioblastoma cells revealed that upon knockout of ring finger protein 138, RPS3 was able to interact with DNA damage-inducible transcript 3 (DDIT3) to induce apoptosis when cells were irradiated." (PMID 40940922, 2025).
ovarian carcinoma (31 papers, 1994 to 2025). A malignant neoplasm originating from the surface ovarian epithelium. "The clinical samples also confirmed that the levels of immune microenvironment markers (CD1α and CD4) and ferroptosis markers (CHMP5 and DDIT3) were lower in high-grade ovarian cancer tissues." (PMID 38178187, 2024). "For ferroptosis markers (CHMP5 and DDIT3), CHMP5 and DDIT3 protein expressions were notably down-regulated in high-grade ovarian cancer tissues." (PMID 38178187, 2024). "Notably, recent reports have shown that tumor-infiltrating CD8+ T cells show excessive DDIT3 expression, which correlates with poor clinical outcomes in patients with ovarian cancer." (PMID 38474084, 2024).
Sepsis (31 papers, 2017 to 2025). Sepsis is defined as life-threatening organ dysfunction caused by a dysregulated host response to infection. "As such, CHOP (DDIT3;GADD153; Gene ID 1649)—an indicator of ER stress —was increased during sepsis (GSE57065 and GSE29536)." (PMID 34439987, 2021).
Cerebral ischemia (28 papers, 2010 to 2025). Restriction of arterial blood supply to the brain associated with insufficient oxygenation to support the metabolic requirements of the tissue. "For example, the expression of chemokine orphan receptor 1(Cmkor 1), DNA-damage-inducible transcript 3 (Ddit 3) and prostacyclin synthase (Ptgis) were found to be enhanced after cerebral ischemia." (PMID 23308210, 2013).
multiple myeloma (28 papers, 2007 to 2025). "Furthermore, we found downregulation of SDC1 and TCF3 and upregulation of DDIT3 in the myeloma cluster, consistent with the observations in MM cell lines." (PMID 36631435, 2023). "In agreement with our findings, bortezomib-evoked apoptosis correlates with the induction of DDIT3 expression in osteosarcoma cells and DDIT3 silencing inhibits death of non-small cell lung cancer and multiple myeloma cells co-treated with nelfinavir and bortezomib." (PMID 34066165, 2021). "Importantly, single-cell analysis of a patient with relapsed/refractory MM confirmed these observations by showing a strong induction of DDIT3 and a concomitant SDC1 reduction, associated with a reduction of the myeloma fraction by >50% after 24 h of NCP26 exposure." (PMID 36631435, 2023).
Hepatic steatosis (25 papers, 2011 to 2026). Steatosis is a term used to denote lipid accumulation within hepatocytes. "Consistently, an increase in DDIT3 gene expression was observed in our liver steatosis model, which diminished with GW4869 treatment." (PMID 38474427, 2024). "Among the different UPR targets tested, CHOP (also known as Ddit3) more consistently predicted elevated plasma cholesterol and hepatic steatosis." (PMID 30733237, 2019).
heart failure (24 papers, 2016 to 2025). Inability of the heart to pump blood at an adequate rate to meet tissue metabolic requirements. "It has been shown that accumulation of misfolded proteins in the ER enhances DDIT3 expression that induces apoptosis in cardiomyocytes, leading to cardiac dysfunction and heart failure." (PMID 35456517, 2022). "Ppp1r15aΔC/ΔC mice lacking Ddit3 showed no protection from irradiation-induced weight loss or heart failure." (PMID 39312445, 2024).
glaucoma (23 papers, 2016 to 2025). Increased pressure in the eyeball due to obstruction of the outflow of aqueous humor. "In conclusion, we demonstrate MKK4/7 controlled RGC soma loss after glaucoma-relevant injury—possibly via somal DDIT3/JUN activation." (PMID 41397991, 2025). "The cellular response to endoplasmic reticulum stress and induction of pro-apoptotic DNA damage inducible transcript 3 (DDIT3, also known as CHOP) have been implicated as drivers of neurodegeneration in many disease models, including glaucoma." (PMID 31632741, 2019). "DDIT3 deficiency promotes optic nerve survival in models of glaucoma, including mechanical optic nerve injury and increased intraocular pressure." (PMID 28969695, 2017). "It is possible, however, that deficiency in both Jun and Ddit3 will protect RGCs in a chronic, ocular hypertensive model of glaucoma." (PMID 28969695, 2017). "Furthermore, identifying the upstream activators of MKK4/7 in the context of glaucoma-relevant injury and elucidating the DDIT3/JUN-independent downstream effectors of MKK4/7 driving loss of somal viability and axonal degeneration will be important next lines of investigation." (PMID 41397991, 2025). "Recently, the transcription factors JUN and DNA-damage inducible transcript 3 (DDIT3, also known as CHOP) were identified as critical regulators of RGC somal loss after glaucoma-relevant injury." (PMID 41397991, 2025). "Previous studies demonstrated that JUN and DDIT3 were important regulators of RGC death after glaucoma-relevant injures." (PMID 32980857, 2020). "RGCs express DDIT3 after glaucoma-relevant insults, and importantly, DDIT3 has been shown to contribute to both RGC somal apoptosis and axonal degeneration after acute induction of ocular hypertension." (PMID 31632741, 2019). "DDIT3 has been shown to regulate RGC death in glaucoma and various other neurodegenerative diseases." (PMID 31632741, 2019). "ER stress, specifically DDIT3, has been implicated as a driver of RGC death after glaucoma-relevant injuries." (PMID 31632741, 2019). "DDIT3 was expressed by RGCs after glaucoma-relevant insults, including optic nerve crush and the microbead model of acute ocular hypertension." (PMID 31632741, 2019). "Future work should focus on the roles of both JUN and DDIT3 together in perpetuating glaucomatous RGC death and should elucidate upstream regulators of both JUN and DDIT3 after glaucoma-relevant injury." (PMID 31632741, 2019). "DDIT3 appears to be an important mediator of RGC viability after glaucoma-relevant injuries." (PMID 31632741, 2019). "Regardless of whether the inciting injury in glaucomatous neurodegeneration is extrinsic or intrinsic to RGCs, sequentially stepping upstream of JUN and DDIT3 activation may define the earliest events in glaucoma." (PMID 28969695, 2017). "Interestingly, if combined deficiency of Jun and Ddit3 protects both RGC axons and somas in a glaucoma model it will point to new transcriptional pathways underlying RGC degeneration in glaucoma." (PMID 28969695, 2017). "Specifically, we examined the dual role of DDIT3 and JUN and their upstream regulators MKK4/7 in controlling RGC death after glaucoma-relevant injury." (PMID 41397991, 2025). "Here, we assessed the importance of DDIT3 and JUN, along with their upstream activators MKK4 and MKK7, in RGC degeneration after glaucoma-relevant injury." (PMID 41397991, 2025). "DDIT3 (also known as CHOP), a pro-apoptotic transcription factor activated after prolonged endoplasmic reticulum stress, moderately contributed to RGC death after glaucoma-relevant insults." (PMID 32980857, 2020). "Here, we investigated the role of DDIT3 in glaucomatous RGC death using an age-related, naturally occurring ocular hypertensive mouse model of glaucoma, DBA/2J mice (D2)." (PMID 31632741, 2019).
glaucoma (continued). "Recent observations suggest that HMA cells play a key role in glaucoma pathology, as it has been found that chronic ER stress induces apoptosis of HRA cells via induction of the PERK/DDIT3 axis of the UPR; this abolishes their neuroprotective potential and leads to glaucoma progression." (PMID 38255802, 2024). "Therefore, it is possible that JUN and/or DDIT3 are RGC-intrinsic regulators of EDN-induced RGC death, similar to after glaucoma-relevant injuries." (PMID 32980857, 2020). "Regardless, our findings suggest that DDIT3 does not play a major role in axonal degeneration in an age-related, chronic ocular hypertension model of glaucoma." (PMID 31632741, 2019). "Therefore, MKK4/7 signaling may be a critical early mechanism governing RGC somal death via DDIT3/JUN activation and may also regulate axonal degeneration after glaucoma-relevant injury." (PMID 41397991, 2025). "Given DBA/2J PERG amplitude decline and soma shrinkage were not prevented with Ddit3/Jun deletion despite robust somal survival, it remained important to assess RGC somal function and size in B6.Mkk4/7−/− eyes after glaucoma relevant injury." (PMID 41397991, 2025).
pancreatic cancer (23 papers, 2013 to 2025). "HCA (200 μM) appeared to activate ER stress/UPR cascades by augmenting the amounts of BiP (GRP-78 or HSPA5) and CHOP (DDIT3, DNA Damage-Inducible Transcript 3) proteins in both pancreatic cancer cell lines and enhancing c-Jun phosphorylation in Ser63 in MIA PaCa-2 cells." (PMID 36077299, 2022). "A pancreatic cancer genomic analysis of pterostilbene revealed downregulation of multiple apoptosis-related genes including MnSOD, DNA-damage-inducible transcript 3 (DDIT-3), and growth differentiation factor 15 (GDF-15), also known as macrophage inhibitory cytokine 1 (MIC-1)." (PMID 23691264, 2013). "It has also been shown the anti-pancreatic cancer activity of celastrol by up-regulating DDIT3 and ATF3 and down-regulating RRM2 and MCM4, however, the role of celastrol in anti-pancreatic cancer remains largely elusive." (PMID 38110764, 2023). "For example, in pancreatic cancer cells, Celastrol plays a cytotoxic role by regulating various gene expressions, mainly through ATF3/DDIT3 overexpression and RRM2/MCM4 downregulation." (PMID 36506508, 2022).